SNORA55 (small nucleolar RNA, H/ACA box 55)
Synonyms: ACA55
Gene: Small nucleolar RNA gene on chromosome 1 (39,567,374 to 39,567,508, reverse strand). Ensembl gene ENSG00000201457.
Gene Ontology:
Biological process: RNA processing
Cellular component: nucleolus
Homologues: Orthologues: chimpanzee SNORA55 (99% identical), macaque SNORA55 (99% identical), pig SNORA55 (91% identical), guinea pig SNORA55 (87% identical), rabbit SNORA55 (87% identical), mouse Gm24620 (83% identical), mouse Gm22154 (81% identical), mouse Gm25788 (81% identical), mouse Gm23974 (79% identical), rat LOC120094473 (70% identical), rat LOC120093962 (66% identical), mouse Gm26048 (58% identical), and 2 more.
Diseases named in the same sentence as SNORA55 in open-access papers:
SNORA55 is named in the same sentence as 2 diseases in open-access papers, as found by Europe PMC text mining. Sharing a sentence is not in itself a finding about the gene and the disease. The quoted sentences say what the papers report.
hepatocellular carcinoma (1 paper, 2025). A malignant tumor that arises from hepatocytes. "TRPM8 similarly supports tumor growth by modulating nuclear-mitochondrial communication; it induces SNORA55 expression, promoting mitochondrial biogenesis and hepatocellular carcinoma proliferation." (PMID 40813985, 2025).
prostate carcinoma (1 paper, 2021). A carcinoma that arises from epithelial cells of the prostate gland. "In addition, a study reported that abnormally high expression of SNORA55 promotes proliferation and migration of prostate cancer cell lines." (PMID 34702132, 2021).